CYFIP1 (cytoplasmic FMR1 interacting protein 1)
Diseases named in the same sentence as CYFIP1 in open-access papers (continued):
Sharing a sentence is not in itself a finding about the gene and the disease.
Stroke (2 papers, 2024 to 2025). Sudden impairment of blood flow to a part of the brain due to occlusion or rupture of an artery to the brain. "CYFIP1 plays a crucial role in stroke recovery by enhancing synaptic plasticity and dendritic remodeling through its regulation of CAMK2A expression, with disruptions in CYFIP1 impairing these neuroprotective effects." (PMID 39595569, 2024).
temporal lobe epilepsy (2 papers, 2016 to 2019). A localization-related (focal) form of epilepsy characterized by recurrent seizures that arise from foci within the temporal lobe, most commonly from its mesial aspect. "Intriguingly, patients with temporal lobe epilepsy and pilocarpine-treated rats show an upregulation of CYFIP1 expression consistent with the notion that increased CYFIP1 expression is associated with altered E/I balance and associated behaviors." (PMID 30784587, 2019). "Furthermore, there is supportive evidence for a role of FMRP in temporal lobe epilepsy: In patients with temporal lobe epilepsy and in rats treated with the seizure-inducing drug pilocarpine, the level of cytosolic FMRP binding protein (CYFIP1) is elevated." (PMID 27855659, 2016).
adenoma (1 paper, 2022). A neoplasm arising from the epithelium. "Despite a lack of direct evidence that inhibition of CYFIP2 contributes to CRC metastasis, a previous study has shown that CYFIP1, which shares 88% amino acid sequence similarity with CYFIP2, was lost in the majority of invasive colon adenocarcinoma tissues compared with noninvasive adenoma tissues." (PMID 35490216, 2022).
albinism (1 paper, 2008). A congenital disorder characterized by partial or complete absence of melanin pigment in the eyes, hair, or skin. "These genomic probes except P2 were generated by PCR amplification from genomic DNAs and are located close to the CpG island of CYFIP1 (P1), the 3'-end of the UBE3A gene (P3), the CpG island of ATP10A (P4), and the CpG island of the P locus for albinism." (PMID 18226259, 2008).
bladder tumors (1 paper, 2017). "CYFIP1 expression has been negatively correlated with the invasion of malignant cells in lung, colon, breast and bladder tumors." (PMID 28410392, 2017).
breast tumors (1 paper, 2021). "Comparing 735 primary breast tumors with 89 healthy breast tissues, we detected significant differential methylation of the candidate CpG site located in CYFIP1 (Wilcoxon test, P value = 9.3 × 10−4)." (PMID 33145876, 2021).
dementia (1 paper, 2021). Loss of intellectual abilities interfering with an individual's social and occupational functions. "One example of a region with conflicting reports overlaps CYFIP1 and NIPA1 where we observed duplications in two Turkish dementia patients." (PMID 34321086, 2021). "Our candidate CNVs overlapping both CYFIP1 and NIPA1 were predicted as likely benign by ClassifyCNV, and we did not observe a significant association with such CNVs and dementia in the UKBB." (PMID 34321086, 2021).
disordered eating (1 paper, 2019). "Our preclinical findings provide evidence that reduced CYFIP1 expression could contribute to OC behaviors and disordered eating." (PMID 31324746, 2019).
HCMV infection (1 paper, 2014). "The interaction with WAVE2, ABI1, ABI2, NAP1, CYFIP1, and talin-1 were validated in conventional immunoprecipitation experiments when pUL135 was expressed in both isolation and the context of HCMV infection." (PMID 25121749, 2014).
mesothelioma (1 paper, 2024). A usually malignant and aggressive neoplasm of the mesothelium which is often associated with exposure to asbestos. "Similarly, CYFIP1 exhibited negative correlations with these immune signatures and showed a poor prognosis in tumors such as BRCA, LUSC, mesothelioma (MESO), sarcoma (SARC), and THCA." (PMID 39408874, 2024).
thyroid carcinomas (1 paper, 2017). "As most thyroid carcinomas did not express ABI3, the correlation among ABI3, WAVE2 and CYFIP1 was not performed in this set of samples." (PMID 28978070, 2017).
tumor (21 papers, 2017 to 2025). "In the present study, we first revealed the role and underlying mechanism of m7G modification derived from CYFIP1 and the tumor-suppressing role of CYFIP1 against OS." (PMID 39984834, 2025). "Of course, we noticed that deletion of PIP5K1A, NCKAP1, and CYFIP1 genes also changes gene expression in certain metabolic pathways, such as cholesterol metabolism, which might also contribute to suppression of tumor cell growth induced by deficiency of these molecules." (PMID 39408874, 2024). "Overall, our in vivo assays align with the observations made in vitro, providing further evidence for the tumor-suppressing role of CYFIP1." (PMID 39984834, 2025). "Cytoplasmic FMR1-interacting protein 1 (CYFIP1), a tumor suppressor, is implicated in tumor migration and invasion by influencing actin nucleation and signaling pathways, such as the β1-integrin/focal adhesion kinase/non-receptor tyrosine kinase axis." (PMID 40747121, 2025). "CYFIP1, a component of the WAVE regulatory complex, is associated with cytoskeletal dynamics and has been reported to act as a tumor suppressor in certain contexts." (PMID 40151638, 2025). "In conclusion, our study demonstrates that CYFIP1 acts as a potent tumor suppressor in OS." (PMID 39984834, 2025). "Additionally, IHC staining was performed on the tumor samples, confirming the overexpression of CYFIP1 in the CYFIP1-stably-expressed OS cells." (PMID 39984834, 2025). "However, there were a few downregulated genes in tumor samples, such as CYFIP1, IFIT5, DCP2, and EIF4E3." (PMID 36761423, 2022). "In sum, the functional role of CYFIP1 in tumor development is still unclear and controversial." (PMID 33145876, 2021). "CYFIP1 expression was correlated with tumor progression in epithelial cancers and it raised the possibility that loss of CYFIP1 might correlate with clinical outcome." (PMID 33145876, 2021). "In addition, some scholars have proposed that CYFIP1 may act as a tumor suppressor gene and may have tumor suppressive function." (PMID 37206976, 2023). "The results confirmed that both CYFIP1 and EMILIN1 were upregulated in tumor tissues, and the knockdown of these two genes affected various tumor phenotypes in NB cells, including colony formation, migration, and invasion." (PMID 38427078, 2024). "Tissue immunohistochemistry revealed an upregulation in the expression of CYFIP1 and EMILIN1 in tumor tissues compared to adjacent normal tissues." (PMID 38427078, 2024). "We found that CYFIP1 is an oncogene in HCC, and its expression in the tissues of HCC patients was higher than in normal tissues in the vicinity of the tumor." (PMID 35620469, 2022). "Subsequently, we performed quantitative reverse-transcription polymerase chain reaction (qRT-PCR) to examine the expression levels of the seven key prognostic genes—CEBPB, TANK, MAT2B, TMEM165, CCDC167, CYFIP1, and COX17—in the CEBPB+CAF prognostic model in the tumor tissues." (PMID 40145099, 2025). "In addition to the decrease in CYFIP1 and WASF2 gene copy numbers in tumor samples, the copy number of other DGs increased to varying degrees, consistent with the decline in CYFIP1 and WASF2 gene expression in BC patients." (PMID 38035071, 2023). "However, CYFIP1 expression has been negatively correlated with patient prognosis in several cancer types (KIRC, KIRP, UCEC), suggesting the tumor repressive role of CYFIP1." (PMID 36226166, 2022).
cancer (19 papers, 2017 to 2025). A tumor composed of atypical neoplastic, often pleomorphic cells that invade other tissues. "Previous studies have implicated dysregulated CYFIP1 expression in certain cancers, particularly with regards to disease progression, including invasion and metastasis." (PMID 39984834, 2025). "The cBioPortal analysis further validated the extensive mutation status of CYFIP1 in multiple cancers." (PMID 40308607, 2025). "Recent studies have demonstrated the significance of CYFIP1 in cancer development, particularly in promoting invasion." (PMID 37654606, 2023). "Except CYFIP1, all CpGDMs in identified cancer genes are in average hypomethylated in leukocytes of BCP compared to healthy women." (PMID 33145876, 2021). "Considering previous studies indicating CYFIP1 as a suppressor of invasion in various cancers, we also explored its role in OS metastasis and found that overexpression of CYFIP1 significantly inhibited the migration of OS cells, which corroborated earlier findings." (PMID 39984834, 2025). "Though CYFIP2 exhibits a high level of similarity to CYFIP1, its biological significance is ambiguous because CYFIP2 expression can be either a protective prognostic factor or a risk factor depending on the specific cancer type." (PMID 39930469, 2025). "Moreover, several recent studies have demonstrated the antitumor effects of CYFIP1 in various cancers." (PMID 39984834, 2025). "Furthermore, hsa-miR-99a which targeting AGO2 was only down-expressed in 8 cancers, while hsa-miR-93 which targeting CYFIP1 was only upregulated in 12 cancers." (PMID 36339001, 2022). "CYFIP1 overexpression may play an important role in cancers with a predominantly altered mTOR signaling pathway." (PMID 36226166, 2022). "CYFIP1 may play an important role in the occurrence and development of cancers." (PMID 33145876, 2021). "Moreover, the regulatory effect of CYFIP1 on WASF3, knockdown in highly invasive cancer cells will lead to inhibition of invasion." (PMID 37206976, 2023). "Given the significant involvement of CYFIP1 and EIF4A1 in cancer pathogenesis, including their potential roles in invasion and protein translation, targeting these molecules may hold promise as a therapeutic approach for OS." (PMID 37654606, 2023). "We found that MHC-I scores were higher in cancer cells without expression of PIP5K1A, NCKAP1, CYFIP1, DIS3, TBP, and EXCO1." (PMID 39408874, 2024).
neurodevelopmental disorder (13 papers, 2012 to 2025). A behavioral and cognitive disorder with onset during the developmental period that involves impaired or aberrant development of intellectual, motor, or social functions. "The human CYFIP1 gene is linked to brain connectivity defects in neurodevelopmental disorders (NDDs)." (PMID 41315480, 2025). "Given the association between CYFIP1 deletion and social deficits in neurodevelopmental disorders (Abekhoukh and Bardoni." (PMID 31324746, 2019). "We further addressed whether increased CYFIP dosage can also directly affect inhibitory and excitatory transmission in neurons, focusing on CYFIP1 as the gene has been more robustly associated with neurodevelopmental disorders." (PMID 30784587, 2019). "This view is complemented by the discovery of neurodevelopmental disorders, which coincide with genetic aberrations in the CYFIP1 locus." (PMID 32486060, 2020). "The CYFIP1 (cytoplasmic FMR1‐interacting protein 1) (OMIM *606322) is involved in neurodevelopmental disorders." (PMID 32368866, 2020). "In this study, we explored functions and interactions of the four protein-coding genes in this region, namely NIPA1, NIPA2, CYFIP1, and TUBGCP5, and elucidate their role, in solo and in concert, in the causation of neurodevelopmental disorders." (PMID 32384786, 2020). "Overall, this study suggests that new models and supplementary analyses are needed to decipher the role of CYFIP1 in the pathophysiology of neurodevelopment and, in particular, in the aetiology of neurodevelopmental disorders." (PMID 28183735, 2017). "For example, CYFIP1, which is an FMR1 interacting protein 1, plays a role in synaptic function and appears to be the gene responsible for 15q11.2-related neurodevelopmental disorders." (PMID 30147856, 2018). "Not surprisingly, CYFIP1 is one of the four paternally deleted genes in patients with type I Prader–Willi syndrome, a neurodevelopmental disorder." (PMID 32368866, 2020).
neurological disorders (7 papers, 2013 to 2025). "Human genetics research has found that cytoplasmic FMR1 interacting protein 1 (CYFIP1) is associated with prominent development and thus participates in a variety of nervous system diseases." (PMID 37206976, 2023). "Thus, CYFIP1 dosage can bi-directionally impact inhibitory synaptic structure and function, potentially leading to altered E/I balance and circuit dysfunction in CYFIP1-associated neurological disorders." (PMID 30784587, 2019). "The identification of interaction partners of CYFIP1 suggests that neurological disorders characterized by spine dysmorphogenesis might be due to perturbations in the balance between these two CYFIP1 interconnected pathways." (PMID 24050404, 2013).
psychiatric disorder (7 papers, 2012 to 2025). A disorder characterized by behavioral and/or psychological abnormalities, often accompanied by physical symptoms. "This may explain why both deletions and duplications of CYFIP1 have been linked to major mental illness." (PMID 24667445, 2014). "We discovered that a reduction in CYFIP1, which mimics the psychiatric disorders seen with 15q11.2 copy number deletion, leads to reduced axonal growth, intracellular calcium concentration, and mitochondrial function." (PMID 41315480, 2025). "Lastly, we assess the current limitations in our understanding of FMRP and CYFIP1 biology and how they must be addressed before mechanism-led therapeutic strategies can be developed for psychiatric disorders." (PMID 34883502, 2020). "It should also be noted that Kittler’s findings derive from both the complete loss and in vitro overexpression of Cyfip1, while our data derives from the constitutive Cyfip1 haploinsufficient mouse, modeling a CNV deletion that confers increased risk to a range of psychiatric disorders." (PMID 31209152, 2019).
brain disorder (6 papers, 2013 to 2022). A disease affecting the brain or part of the brain. "The CYFIP1 interactome reveals many interactors associated with brain disorders, opening new perspectives to define regulatory pathways shared by neurological disabilities characterized by spine dysmorphogenesis." (PMID 24050404, 2013). "More importantly, genetic variants of CYFIP1 and CYFIP2 are associated with different types of brain disorders." (PMID 31853374, 2019). "Recent molecular genetic studies have suggested that two members of the cytoplasmic FMR1-interacting protein (CYFIP) gene family, CYFIP1 and CYFIP2, are causally associated with several brain disorders." (PMID 31853374, 2019). "In addition, three of the four genes (CYFIP1, NIPA1, and NIPA2) have been shown to play a role in neurodevelopment and are associated with brain disorders." (PMID 34970295, 2021). "Both CYFIP1 and CYFIP2 genes are associated with various brain disorders." (PMID 33192297, 2020). "However, the detailed mechanisms underlying the in vivo differences between CYFIP1 and CYFIP2 remain largely unexplored, which is an important issue toward understanding the pathophysiology of and potential treatments for various CYFIP-associated brain disorders." (PMID 31853374, 2019).
CYFIP1 also shares sentences with these, for which no sentence is quoted: colon cancer (2 papers); Depression (2); glioma (2); speech delay (2); type 2 diabetes (2); attention deficit-hyperactivity disorder (1); bipolar disorder (1); cardiovascular diseases (1); carotid atherosclerosis (1); childhood absence epilepsy (1); Cognitive impairment (1); colon adenocarcinoma (1); congenital heart disease (1); developmental disabilities (1); Down syndrome (1); dyslexia (1); follicular thyroid carcinoma (1); frontotemporal lobar degeneration (1); Insulin resistance (1); liver fibrosis (1); lung carcinoma (1); microcephaly (1); nasopharyngeal carcinoma (1); neuroblastoma (1); osteosarcoma (1); paraplegia (1); Salmonella Infections (1); sarcoma (1); Spastic paraplegia (1); Spastic paraplegia 6 (1).